S1PR1 (sphingosine-1-phosphate receptor 1)
Diseases named in the same sentence as S1PR1 in open-access papers (continued):
Sharing a sentence is not in itself a finding about the gene and the disease.
inflammatory bowel disease (11 papers, 2016 to 2024). A spectrum of small and large bowel inflammatory diseases of unknown etiology. "This is of great importance as the blockade of the S1P/S1PR1 axis is emerging as a new therapeutic approach to control the aberrant leukocyte migration into the mucosa in inflammatory bowel disease." (PMID 33102475, 2020). "Modulation of S1PR1 has established a new approach in the treatment of autoimmune diseases, such as multiple sclerosis (MS), inflammatory bowel disease (IBD), lupus, and psoriasis." (PMID 36071831, 2022). "S1PR1 antagonists/agonists are also tested for other conditions besides MS, including psoriasis, graft vs. host disease (GVHD) and inflammatory bowel diseases (IBD)." (PMID 30828332, 2019). "By preventing T lymphocytes with self-reactive receptors from entering target tissues, pharmacological agents targeting the S1P/S1PR1 axis have shown efficacy in the treatment of autoimmune diseases including multiple sclerosis, rheumatoid arthritis, and inflammatory bowel disease (IBD)." (PMID 29333002, 2017).
lung carcinoma (11 papers, 2016 to 2025). "Utilizing database analysis and tissue sample evaluation, we initially verified that S1PR1 is downregulated in lung cancer and is closely associated with patient prognosis." (PMID 39551792, 2024). "On the other hand, low S1PR1 expression is suggested to be linked to poor prognosis in breast and lung cancer." (PMID 34503284, 2021). "Based on the consistent results for the associations between S1PR1 expression and survival in breast and lung cancers, we focused on the precise effects of S1PR1 in these two cancer types, as well as the underlying mechanisms." (PMID 32799825, 2020). "However, the current understanding of the precise role and underlying mechanisms of S1PR1 in lung cancer remains incomplete." (PMID 39551792, 2024). "Studies have revealed that S1PR1 in lung cancer tissues exhibits a pronounced downward trajectory compared to normal lung tissues, and this reduced expression is intimately associated with an unfavorable prognosis for lung cancer patients." (PMID 39551792, 2024). "Supporting this, tumor endothelial S1PR1 overexpression normalizes vasculature while influencing tumor growth and metastasis in lung cancer, highlighting context-dependent receptor roles across tumor types." (PMID 40137142, 2025). "The exact role of the S1PR1 signaling pathway in lung cancer metastasis still needs further research and exploration." (PMID 36714534, 2023). "We found that lung cancer tissues expressed mainly S1PR1, S1PR2 and S1PR3, whereas S1PR4 and S1PR5 were undetectable, probably because they are highly restricted to distinct cell types and tissues, such as the lymphoid tissues, brain, and spleen." (PMID 37446018, 2023). "Our results shed light on the important role of S1PR1 in breast and lung cancer, and determined that it is closely related to tumor immunity." (PMID 32799825, 2020). "S1PR1 expression was remarkably lower in breast and lung cancer tissues than in the corresponding normal tissues." (PMID 32799825, 2020). "The correlation between S1PR1 expression and immune cell marker genes suggests that S1PR1 regulates lung cancer tumor immunity through multiple immune cell populations." (PMID 32799825, 2020). "S1PR1 was related to immune infiltration in lung cancer, including LUAD (tumor purity; r = − 0.353, P = 6.05e-16) and LUSC (tumor purity; r = − 0.402, P = 5.20e-20)." (PMID 32799825, 2020). "To further elucidate the molecular mechanisms underlying the role of S1PR1 in breast and lung cancers, we used GSEA to identify pathways that are enriched in genes co-expressed with S1PR1." (PMID 32799825, 2020). "In conclusion, decreased S1PR1 expression was related to poor prognosis together with reduction of effect immune cell infiltration in breast and lung cancers." (PMID 32799825, 2020). "Down‐regulation of S1PR1 was observed in lung carcinoma as compared to normal lung tissue, and the metastatic potential of a lung cancer cell line was correlated with lower S1PR1 levels." (PMID 27239439, 2016). "In addition, the SK1/S1P/S1PR2 signaling pathway leads to imatinib resistance in chronic myeloid leukemia (CML), and the SK2/S1P/S1PR1/S1PR3 signaling pathway renders the A549 lung cancer cell line resistant to etoposide." (PMID 40069781, 2025). "Therefore, in this study, we analyzed the differential expression of S1PR1 in lung cancer tissues compared to normal lung tissues using database analysis followed by experimental validation." (PMID 39551792, 2024). "Additionally, S1PR1 expression is reduced in pulmonary microvascular endothelial cells isolated from chronic smokers compared to non-smokers, suggesting that S1PR1 deficiency may contribute to the development of lung cancer, given that smoking is a well-established risk factor for this malignancy." (PMID 39551792, 2024).
lung carcinoma (continued). "To further elucidate the underlying mechanism of S1PR1’s regulation of FOXA1, we conducted a comprehensive search using Targetscan, miRTarbase, and miRDB databases to identify the microRNAs (miRNAs) that modulate FOXA1 in lung cancer tissues or cells." (PMID 39551792, 2024). "S1PR1 levels are positively correlated with multiple immune markers in breast and lung cancer." (PMID 32799825, 2020). "These observed correlations between S1PR1 and various types of immune cells in breast and lung cancers indicated that S1PR1 may have high prognostic value." (PMID 32799825, 2020). "In addition, low S1PR1 expression was also related to poor prognosis in two cohorts of patients with lung cancer (GSE31210 and GSE8894), as determined using two probes (204642_at and 239401_at)." (PMID 32799825, 2020). "Taken together, high expression of S1PR1 could be considered a good prognostic indictor for breast and lung cancers depending on the clinical characteristics." (PMID 32799825, 2020). "We further analyzed the expression of S1PR1 in breast and lung cancers." (PMID 32799825, 2020). "In particular, low S1PR1 mRNA expression was correlated with worse OS in stage 1 (P = 9.20E-13) and early-stage (AJCC stage M) (P = 0.013) lung cancer." (PMID 32799825, 2020). "The evaluation of immune cell infiltration in breast and lung cancers using the TIMER database revealed strong negative correlations between S1PR1 and tumor purity in BRCA, LUAD, and LUSC." (PMID 32799825, 2020). "In lung-cancer-related studies, it was found that the proliferation and invasion of NSCLC cells in vitro and tumor growth in vivo could be promoted by up-regulating the expression of S1PR1." (PMID 38794152, 2024). "Indeed, we demonstrated that S1PR1, S1PR2, S1PR3, and S1PR5, but not S1PR4 are correlated with worse lung cancer patient prognosis." (PMID 35897763, 2022).
pulmonary fibrosis (11 papers, 2014 to 2025). Chronic progressive interstitial lung disorder characterized by the replacement of the lung tissue by connective tissue, leading to progressive dyspnea, respiratory failure, or right heart failure. "Dysregulation of the SPHK1-S1p-S1PR1 axis has been linked to pathological inflammation and tissue remodeling, but its role in fibrocyte-mediated pulmonary fibrosis remains unclear." (PMID 40573254, 2025). "Our study indicates that SPHK1-S1p-S1PR1 signaling is a critical regulator of fibrocyte-mediated pulmonary fibrosis." (PMID 40573254, 2025). "In 2020 and 2022, they used the same murine model with bleomycin-induced pulmonary fibrosis and focused on the results of endothelial-specific deletion of S1PR1." (PMID 37371823, 2023). "In mouse models of lung fibrosis, S1PR1 was shown to inhibit lung fibrosis whereas S1PR3 mediated the development of lung fibrosis." (PMID 29782549, 2018). "Moreover, the pharmacological inhibition of SPHK1 or the functional antagonism of S1PR1 disrupted fibrocyte trafficking, reduced extracellular matrix deposition, and ameliorated lung fibrosis, underscoring the therapeutic potential of targeting this pathway." (PMID 40573254, 2025). "The increased prevalence of S1PR2- and S1PR3- but not S1PR1-specific aAb in SSc-PAH patients may thus point towards an autoimmune-supported pathomechanism that could contribute to elevated pulmonary vascular resistance and the development of lung fibrosis in SSc-associated PAH." (PMID 35860272, 2022).
asthma (10 papers, 2015 to 2025). "Functional variants have been associated with asthma susceptibility, constituting a risk factor for disease severity, which supports the idea that genetic variants of S1PR1 may influence physiological and pathological events in the lung compartment." (PMID 32127447, 2020). "Accordingly, miR-155 was described to stimulate the TH2 response and mucus hypersecretion by directly targeting sphingosine-1-phosphate receptor 1 and cytotoxic T lymphocyte–associated antigen 4 in CD4+ cells in experimental models of asthma." (PMID 31805682, 2019). "To evaluate the effect of VPC23019, S1PR1 and S1PR3 antagonist, on experimental asthma, we carried out histologic analyses of the bronchus at 24 h after the last challenge." (PMID 30192865, 2018). "Finally, the anti-inflammatory effect of VPC 23019, S1PR1/3 antagonist, in the OVA-induced asthma was examined." (PMID 30192865, 2018). "In our study, S1PR1 and S1PR4 were the main receptors expressed in asthmatic PBMCs, while S1PR4 was the only elevated receptor after standardized management and treatment of asthma, indicating to a predictable effect on the pathophysiology of asthma, especially in the immune response." (PMID 37056936, 2023).
cardiac hypertrophy (10 papers, 2017 to 2025). "Endothelial‐specific deletion of S1pr1 significantly aggravated cardiac dysfunction and deteriorated cardiac hypertrophy and fibrosis in myocardium." (PMID 31854513, 2020). "S1PR1 signaling regulates blood flow and pressure, induces cardiac hypertrophy and fibrosis and building of atherosclerotic plaques." (PMID 30949477, 2019). "Our model is the first transgenic mouse model in which stimulation of local RAS in fibroblasts results in ventricular hypertrophy and fibrosis through S1PR1- and AT1-dependent IL-6 release from fibroblasts." (PMID 28771545, 2017). "Our data show the crucial role of S1PR1-mediated lysophospholipid signaling in cardiac fibroblasts for cardiac hypertrophy and fibrosis." (PMID 28771545, 2017). "Mechanistically, S1PR1-mediated cardiac hypertrophy is characterized by total dependence on Ang II-AT1 axis and IL-6." (PMID 28771545, 2017). "The loss of S1pr1 in CMs induced by tamoxifen in adult mice did not affect post-MI cardiac hypertrophy, as demonstrated by the heart weight to body weight ratio and WGA staining, nor did it influence cardiac microvessel density, as shown by IB4 staining." (PMID 39816679, 2025). "In mouse experiments, S1PR1 expression is upregulated during myocardial hypertrophy and can lead to myocardial hypertrophy and fibrosis by inducing interleukin (IL)-6 secretion in a manner dependent on Ang II-AT1, though this occurs only in proliferating fibroblasts and not in cardiac myocytes." (PMID 38015241, 2024). "Finally, pharmacological activation of S1pr1 ameliorated TAC‐induced cardiac hypertrophy and fibrosis, leading to an improvement in cardiac function." (PMID 31854513, 2020). "We demonstrated that one potential explanation may be due to impaired AKT/eNOS signalling in S1pr1‐deficient mice, as in vitro experiments showed that inhibition of AKT/eNOS reversed the inhibitory effect of S1pr1 on cardiac hypertrophy." (PMID 31854513, 2020). "Another loss of function mutation approach using fibroblast-specific S1PR1 gene deletion would be informative in understanding a role of S1PR1 in cardiac hypertrophy and may provide a new insight into therapeutic clues for preventing cardiac fibrosis." (PMID 28771545, 2017). "We found in the transgenic (TG) mice that augmented S1PR1 signaling in myofibroblasts led to the development of pathological cardiac hypertrophy with interstitial fibrosis, which was mediated through the paracrine actions of Ang II and interleukin-6 (IL-6) released by myofibroblasts." (PMID 28771545, 2017). "Furthermore, pharmacological activation of S1pr1 significantly ameliorated pressure overload‐induced cardiac hypertrophy and fibrosis, and therefore improved cardiac function in vivo, suggesting that EC‐S1pr1 signals as a potential target to therapy heart failure." (PMID 31854513, 2020). "AMPK/SIRT1 pathway activation by S1pr1 regulation decreased ISO-induced ERS and cardiac hypertrophy." (PMID 40191425, 2025). "Further studies showed that S1P/S1pr1 praxis activated AKT/eNOS signalling pathways and enhanced the production of NO, which contributed to the protective effect of EC‐S1pr1 on cardiac hypertrophy and fibrosis." (PMID 31854513, 2020). "Pharmacological activation of S1pr1 by S1pr1 agonist, SEW2871 (5 mg/kg/d) for 4 weeks significantly reduced cardiac hypertrophy, as shown by the ratio of HW (heart weight)/BW (bodyweight) and LV mass measured by echocardiography." (PMID 31854513, 2020). "A major finding of the present study is the significant aggravation of cardiac hypertrophy in mice lacking S1pr1 in endothelial cells after TAC operation." (PMID 31854513, 2020). "Augmented S1PR1 action due to αSMA promoter-driven S1PR1 overexpression in mice leads to cardiac hypertrophy and fibrosis with reduced contractility in the absence of hemodynamic stress." (PMID 28771545, 2017). "Activation of S1PR3, which couples to Gq and G12/13 unlike S1PR1, might lead to cardiac fibrosis without hypertrophy." (PMID 28771545, 2017).
cardiac hypertrophy (continued). "Similarly, wheat germ agglutinin (WGA) immunostaining indicated that CM-specific S1pr1 deletion induced by tamoxifen in neonates did not alter cardiomyocyte cross-sectional area following AR, suggesting that the CM-S1PR1 deletion does not influence cardiac hypertrophy in our animal models." (PMID 39816679, 2025).
endothelial dysfunction (9 papers, 2013 to 2025). In vascular diseases, endothelial dysfunction is a systemic pathological state of the endothelium (the inner lining of blood vessels) and can be broadly defined as an imbalance between vasodilating and vasoconstricting substances produced by (or acting on) the endothelium. "Taken together, these results show that Smyd2 enhances Sphk and S1PR3 expression and negatively regulates S1PR1 expression, resulting in endothelial dysfunction." (PMID 35297562, 2022). "CD69 induction during endothelial dysfunction may drive exaggerated inflammation by antagonizing the endothelial protective S1PR1 pathway." (PMID 40617350, 2025). "S1P also antagonizes endothelial dysfunction by preventing monocyte/endothelial interactions through activation S1PR1 in the type 1 NOD mouse model and has vascular protective properties, whereas S1PR1 activation promotes eNOS activation and nitric oxide production." (PMID 23360427, 2013). "In PE endothelial cells, the increased expression of Nogo-B, SPPase, and S1P lyase, together with the decreased S1PR1 expression and concomitant S1PR2 upregulation, indicate the onset of an endothelial dysfunction, typical of this disorder." (PMID 32033121, 2020).
experimental autoimmune encephalomyelitis (9 papers, 2012 to 2022). An autoimmune demyelinating disease of the central nervous system that is produced experimentally in animals by the injection of homogenized brain or spinal cord in Freund's adjuvant. "The selective deletion of S1PR1 from astrocytes also reduces experimental autoimmune encephalomyelitis (EAE)-related phenotypic severity and histological abnormalities, including demyelination and astrogliosis." (PMID 32127495, 2020). "This tracer showed the capability to detect the increase of S1PR1 expression in rat lumbar spinal cord in an experimental autoimmune encephalomyelitis model of MS." (PMID 31659498, 2019). "S1PR1 was previously reported to be up-regulated in neurons in focal ischemic mice model and astrocytes in experimental autoimmune encephalomyelitis mice model." (PMID 26367258, 2015).
Hypertension (9 papers, 2012 to 2023). The presence of chronic increased pressure in the systemic arterial system. "Administration of fingolimod (FTY720), which is a non-selective S1PR1, 3, 4, 5 agonist, increased the blood pressure in normotensive C57BL/6 mice and exacerbates hypertension in AngII mouse model, underlining the antihypertensive function of S1PR1 signaling." (PMID 36119733, 2022). "Additionally, a study reported that the loss of endothelial S1PR1 expression in resistance arteries via fingolimod treatment, abolishes vasorelaxation, increases blood pressure in control mice, and exacerbates hypertension in the Ang-II mouse model." (PMID 36160839, 2022). "Accordingly, pharmacologically blocking S1PR1 by fingolimod, which is considered an immunosuppressant, attenuates the development of hypertension and renal damage in our mouse model." (PMID 36160839, 2022). "We successfully analyzed the role of S1PR1 in hypertension-induced end-organ damage by detecting secreted pro-inflammatory cytokines secreting memory T cells infiltrating the kidney." (PMID 36160839, 2022). "This is evidenced that in angiotensin II mouse model, functional S1PR1 antagonism using fingolimod‐reduced S1PR1 expression in mouse endothelium and thus exacerbated hypertension, highlighting the potential harmful effects of fingolimod on vascular function." (PMID 32803879, 2020). "Mice lacking Nogo-B specifically in the endothelium are protected from hypertension and heart failure, mainly via the upregulation of endothelial-derived S1P S1PR1 signaling." (PMID 32033121, 2020). "Therefore, we aimed to determine the role of T cell S1PR1 in hypertension in response to repeated hypertensive challenges." (PMID 36160839, 2022). "Furthermore, studies conducted on mice demonstrated that S1PR1 (sphingosine-1-phosphate receptor 1) signaling might be considered as a novel therapeutic option for hypertension via vascular relaxation." (PMID 35216351, 2022). "Overall, we showed that pharmacological blockade of the S1PR1 expressed by the TEM cells locks this population in the bone marrow and weakens the severity of hypertension and kidney damage." (PMID 36160839, 2022). "To determine the role of S1PR1 in hypertension-induced end-organ damage and reactivation and trafficking of TEM cells in response to repeated high salt stimulation, we used the immunosuppressant fingolimod, a functional antagonist for S1PR1." (PMID 36160839, 2022). "Herein, we hypothesized that S1PR1 plays an essential role in the egress of TEM cells from the bone marrow to the kidney and that pharmacological blockade of S1PR1 by fingolimod prevents renal damage and hypertension onset in response to repeated high salt stimuli." (PMID 36160839, 2022).